ENSG00000290955 (novel transcript)
Gene: Long non-coding RNA gene on chromosome X (36,678,678 to 36,985,693, reverse strand). Ensembl gene ENSG00000290955.
Gene Ontology:
Biological process: SRP-dependent cotranslational protein targeting to membrane, signal sequence recognition
Cellular component: signal recognition particle, endoplasmic reticulum targeting